RNU6-947P (RNA, U6 small nuclear 947, pseudogene)
Gene: Small nuclear RNA gene on chromosome 1 (244,954,858 to 244,954,963, forward strand). Ensembl gene ENSG00000252073.
Homologues: Orthologues: macaque U6 (86% identical), chimpanzee U6 (78% identical), mouse Gm25522 (58% identical). Paralogues in human: RNU6-266P (77% identical), RNU6-1181P (76% identical), RNU6-71P (76% identical), RNU6-949P (76% identical), RNU6-17P (75% identical), RNU6-18P (75% identical), RNU6-283P (75% identical), RNU6-42P (75% identical), RNU6-1 (75% identical), RNU6-1024P (75% identical), RNU6-1099P (75% identical), RNU6-10P (75% identical), and 1285 more.